HTR2C (5-hydroxytryptamine receptor 2C)
Description:
G protein-coupled receptor for 5-hydroxytryptamine (serotonin). Also functions as a receptor for various drugs and psychoactive substances, including ergot alkaloid derivatives, 1-2,5,-dimethoxy-4-iodophenyl-2-aminopropane (DOI) and lysergic acid diethylamide (LSD). Ligand binding causes a conformation change that triggers signaling via guanine nucleotide-binding proteins (G proteins) and modulates the activity of downstream effectors. HTR2C is coupled to G(q)/G(11) G alpha proteins and activates phospholipase C-beta, releasing diacylglycerol (DAG) and inositol 1,4,5-trisphosphate (IP3) second messengers that modulate the activity of phosphatidylinositol 3-kinase and promote the release of Ca(2+) ions from intracellular stores, respectively. Beta-arrestin family members inhibit signaling via G proteins and mediate activation of alternative signaling pathways. Regulates neuronal activity via the activation of short transient receptor potential calcium channels in the brain, and thereby modulates the activation of pro-opiomelanocortin neurons and the release of CRH that then regulates the release of corticosterone (By similarity). Plays a role in the regulation of appetite and eating behavior, responses to anxiogenic stimuli and stress (By similarity). Plays a role in insulin sensitivity and glucose homeostasis (By similarity).
Synonyms: 5-HT2C; 5-HTR2C; 5-HT1C; HTR1C; 5HTR2C
Tractability: Small molecule: an approved drug acts on it; a structure with a bound ligand is known; a high-quality ligand is known; it belongs to a druggable protein family. Antibody: UniProt places it where antibodies can reach, with high confidence; its Gene Ontology location is reachable by antibodies, with high confidence; UniProt predicts a signal peptide or a membrane-spanning region. PROTAC: a small molecule that binds it is known.
Target class: Monoamine receptor; Family A G protein-coupled receptor; Small molecule receptor (family A GPCR); Serotonin receptor; Membrane receptor
Chemical probes: BI-3234 (high quality), BI-4752 (high quality), CHEMBL3416063, CHEMBL570274, NBOH-2C-CN (high quality)
Safety:
Unwanted effects reported when the protein is acted on. In parentheses: how it was acted on, where the effect was seen, and who reports it.
abnormal mouth movements (activation, acute dosing; nervous system; source: Lynch et al. (2017))
decreased anxiety (inhibition, acute dosing; nervous system; source: Lynch et al. (2017))
decreased convulsions (inhibition, acute dosing; nervous system; source: Lynch et al. (2017))
decreased eating (activation, acute dosing; nervous system; source: Lynch et al. (2017))
decreased locomotor activity (activation, acute dosing; nervous system; source: Lynch et al. (2017))
decreased memory (activation, acute dosing; nervous system; source: Lynch et al. (2017))
drug abuse/dependence (inhibition, acute dosing; nervous system; source: Lynch et al. (2017))
increased anxiety (activation, acute dosing; nervous system; source: Lynch et al. (2017))
increased convulsions (activation, acute dosing; nervous system; source: Lynch et al. (2017))
increased memory (inhibition, acute dosing; nervous system; source: Lynch et al. (2017))
Increased, Kidney Failure (activation; source: AOP-Wiki)
penile erection (activation, acute dosing; nervous system; source: Lynch et al. (2017))
antipsychotic-induced weight gain (source: ClinPGx)
metabolic syndrome (source: ClinPGx)
weight gain (source: ClinPGx)
Gene: Protein-coding gene on chromosome X (114,584,078 to 114,910,061, forward strand). Ensembl gene ENSG00000147246.
Subcellular location: Cell membrane
Pathways (Reactome):
Signal Transduction: G alpha (q) signalling events; Serotonin receptors
Gene Ontology:
Molecular function: 1-(4-iodo-2,5-dimethoxyphenyl)propan-2-amine binding; G protein-coupled serotonin receptor activity; Gq/11-coupled serotonin receptor activity; identical protein binding; protein binding; serotonin binding; neurotransmitter receptor activity; G protein-coupled receptor activity
Biological process: G protein-coupled serotonin receptor signaling pathway; intracellular calcium ion homeostasis; phospholipase C-activating serotonin receptor signaling pathway; positive regulation of ERK1 and ERK2 cascade; positive regulation of phosphatidylinositol biosynthetic process; release of sequestered calcium ion into cytosol; behavioral fear response; chemical synaptic transmission; feeding behavior; G protein-coupled receptor signaling pathway, coupled to cyclic nucleotide second messenger; phospholipase C-activating G protein-coupled receptor signaling pathway; regulation of appetite; regulation of corticotropin-releasing hormone secretion; regulation of nervous system process; serotonin receptor signaling pathway; G protein-coupled receptor signaling pathway; locomotory behavior
Cellular component: G protein-coupled serotonin receptor complex; plasma membrane; dendrite; membrane; synapse
Homologues: Orthologues: chimpanzee HTR2C (99% identical), macaque HTR2C (98% identical), pig HTR2C (95% identical), dog HTR2C (93% identical), guinea pig HTR2C (93% identical), rabbit HTR2C (93% identical), mouse Htr2c (91% identical), tropical clawed frog htr2c (57% identical), zebrafish htr2cl1 (52% identical), zebrafish htr2cl2 (41% identical), Drosophila melanogaster 5-HT2A (33% identical), Caenorhabditis elegans ser-6 (15% identical). Paralogues in human: HTR2A (50% identical), HTR2B (42% identical), HTR1E (23% identical), HTR6 (23% identical), HTR7 (23% identical), HTR1B (22% identical), HTR1F (22% identical), HTR5A (21% identical).
Diseases named in the same sentence as HTR2C in open-access papers:
HTR2C is named in the same sentence as 94 diseases in open-access papers, as found by Europe PMC text mining. Sharing a sentence is not in itself a finding about the gene and the disease. The quoted sentences say what the papers report.
Obesity (35 papers, 2007 to 2025). Accumulation of substantial excess body fat. "HTR2C, the serotonin 2C receptor, is another protein that is linked to both obesity and advanced brain functions." (PMID 37371369, 2023). "Among RAI1 target genes are Bdnf (brain-derived neurotrophic factor) and Htr2c (serotonin receptor 2c), both of which are implicated in hyperphagia leading to obesity, a phenotype accompanying SMS, concomitant with altered locomotor activity." (PMID 28548639, 2017). "Mouse studies and the development of weight-loss drugs like Fen-Phen validated the serotonin receptor 2C (HTR2C) protein as an anti-obesity drug target." (PMID 23494383, 2013). "The loss-of-function variants in the HTR2C gene (encoding the HT2CR protein) could lead to the development of obesity in humans." (PMID 37371369, 2023). "Htr2c antagonists are being explored for their potential in treating obesity and metabolic disorders." (PMID 39569210, 2024). "Six genes (CNR2, DPP4, GLP1R, SLC5A1, HTR2C, MCHR1) that encode therapeutic targets in development of type 2 diabetes or obesity." (PMID 36902588, 2023). "The early developmental deletion of LepRb from vGat or Nos1 neurons produced dramatic obesity, but deletion of LepRb from Pomc, Agrp, Ghrh, or Htr2c neurons minimally altered energy balance." (PMID 29914853, 2018). "Interestingly, in addition to seizure susceptibility, Ff/+ heterozygotes display two nonseizure phenotypes like those of Htr2c null mutants: mild hyperactivity and late-onset obesity." (PMID 17677002, 2007).
Anxiety (32 papers, 2012 to 2025). Intense feelings of nervousness, tension, or panic often arise in response to interpersonal stresses. "Prior studies indicate that Htr2c knockout can reduce anxiety-like behavior by dampening amygdala signaling, highlighting a potential role of Htr2c upregulation in anxiety during withdrawal." (PMID 40518557, 2025). "The physiological pathways of anxiety associated with the expression of BDNF, HTR2C, MAOA, and RGS2 can be affected by miR-22 and the repetitive behavior in heterozygous knocked-out mice can be prompted by the partial loss of miR-137." (PMID 36344488, 2022). "This G-protein-coupled serotonin receptor, HTR2C, is involved in demonstrating anxiety-like behavior." (PMID 35740098, 2022). "Involvement of other 5-HT receptors including HTR1B, HTR1B, and HTR2C in the mechanisms of anxiety have also been recognized." (PMID 33178009, 2020). "We first searched for significant correlations between anxiety-like behavior and gene expression in all mice combined and found that Trkb, Htr2c, Adcy5, and App were negatively correlated with anxiety-like behavior." (PMID 24199867, 2013). "The correlation patterns based on hormone treatment were fairly week, with only Htr2c and App being negatively correlated with anxiety-like behavior in testosterone-treated mice." (PMID 24199867, 2013). "Htr2c expression was also downregulated in the DHP and the EC (DHP: t6 = 3.22, p < 0.05; EC: t7 = 2.78, p < 0.05), which is a receptor that has been implicated in anxiety-like behavior and hyperlocomotion in the dorsal (anterior) hippocampus." (PMID 37009893, 2023). "However, our finding that Htr2c expression was negatively correlated with anxiety-like behavior overall and in gonadal females is consistent with these previous reports." (PMID 24199867, 2013). "Targeted alteration (knock-in) of the Htr2c gene to generate ‘INI’ mice with no alternate splicing, solely expressing the full-length unedited isoform, did not produce an overt metabolic phenotype or altered anxiety behaviour, but did display reduced depressive-like and fear-associated behaviours." (PMID 25257581, 2014).
depression (32 papers, 2010 to 2025). "Previous studies have demonstrated the close relationship between mental illnesses and serotonin deficiencies, and also found that Htr2c is a neuromodulator that involves in psychiatric behaviors such as clinical depression." (PMID 35502892, 2022). "Htr2c is seemingly involved in depressive disorders, and its mRNA expression is abundant in the dorsal-ventral axis of the murine hippocampus." (PMID 36982837, 2023). "A number of DEGs detected in this study have also been associated with altered neuronal function, including reduced HTR2A and increased HTR2C expression in individuals suffering from depression and Huntington’s disease." (PMID 27809765, 2016). "Finally, although the QTL for digging behavior on the X-chromosome was very broad, notable genes in this locus included Dcx, coding for neuronal migration protein doublecortin, and Htr2C gene, coding for a serotonin receptor implicated in mental illnesses including OCD and depression." (PMID 30559955, 2018). "Accordingly, reduced Htra1 and Htr2c expressions in XY mice are consistent with the increased depressive-like behaviors observed in that group and together suggests a sexual dimorphism aspect to the low serotonin hypothesis of depression." (PMID 24199867, 2013).
schizophrenia (18 papers, 2013 to 2025). A major psychotic disorder characterized by abnormalities in the perception or expression of reality. "According to a systematic review, for FTO and leptin and leptin receptor genes (LEP and LEPR), for the methylenetetrahydrofolate reductase (MTHFR) gene, and for the serotonin receptor 2C gene (HTR2C), there is strong evidence of association with MetS in schizophrenia patients." (PMID 38540239, 2024). "A decreased expression of Htr2c in the mPFC of schizophrenia patients was also reported suggesting that alterations in the expression level of Htr2c are a common regulatory mechanism in different adaptive situations." (PMID 38920671, 2024). "This study aimed to examine molecular associations of HTR1A, HTR1B, HTR2A, HTR2C and HTR6 gene polymorphisms with acute EPS in 229 male schizophrenia patients, following two weeks of haloperidol monotherapy." (PMID 32231051, 2020). "The present paper describes the results of an association study of in the end 24 polymorphic variants of HTR1A, HTR1B, HTR2A, HTR2C, HTR3A, HTR3B, and HTR6 genes with TD and two of its subtypes in 449 patients with schizophrenia." (PMID 32390801, 2020). "In addition, genetic variants potentially contributing to the high comorbidity of MetS and schizophrenia were found in the genes of the leptin receptor and the serotonin receptor 2C (HTR2C)." (PMID 31798479, 2019). "A set of 29 SNPs of genes of serotonin receptors HTR1A, HTR1B, HTR2A, HTR2C, HTR3A, HTR3B, and HTR6 was studied in a population of 449 Caucasians (226 females and 223 males) with verified clinical diagnosis of schizophrenia (according to ICD-10: F20)." (PMID 32390801, 2020).
mental disorder (7 papers, 2018 to 2023). A disease that has its basis in the disruption of mental process. "Single nucleotide polymorphisms(SNPs) from the serotonin 2C receptor gene (HTR2C) have beenassociated with several neurological and mental disorders, includingabnormalities in cognitive and emotional processes." (PMID 29924134, 2018). "GSK3B, BDNF, NGF, NRG1, HTR2C, and PIP4K2A play important roles in molecular mechanisms of psychiatric disorders." (PMID 33193575, 2020). "GSK3B, BDNF, NGF, NRG1, HTR2C, and PIP4K2A are genes that showed some importance in the study of the molecular etiology of psychiatric disorders." (PMID 33193575, 2020).
metabolic syndrome (7 papers, 2014 to 2025). A cluster of metabolic risk factors for CARDIOVASCULAR DISEASES and TYPE 2 DIABETES MELLITUS. "In attempts to identify genetic vulnerability to antipsychotic induced weight gain and metabolic syndrome, HTR2C, encoding the 5-HT2C receptor, has yielded the most reliable associations." (PMID 24885933, 2014).
epilepsy (5 papers, 2007 to 2023). A brain disorder characterized by episodes of abnormally increased neuronal discharge resulting in transient episodes of sensory or motor neurological dysfunction, or psychic dysfunction. "The Htr2c knockout mouse has a complicated phenotype that includes disruptions in appetite control, epilepsy, and diabetes." (PMID 21984899, 2011).
autism (4 papers, 2012 to 2023). Persistent deficits in social interaction and communication and interaction as well as a markedly restricted repertoire of activity and interest as well as repetitive patterns of behavior. "Since the serotonin system was reported to relate to autism, the regulation of MBD1 on Htr2c is likely to contribute to autism." (PMID 25751725, 2015). "Finally, three CvI-unique are also registered in the Autism KB database: Htr2c, Rbfox2 (an RNA binding protein), and Txk (a tyrosine kinase)." (PMID 27782041, 2016).
bipolar disorder (4 papers, 2018 to 2025). A disorder of the brain that causes unusual shifts in mood, energy, activity levels and the ability to carry out day-to-day tasks. "Supporting a developmental origin of these changes, several linkage studies have described an association between bipolar disorder and single nucleotide polymorphisms in genes such as TPH2, HTR1A, HTR2A, HTR2C or SLC6A450–55." (PMID 30087403, 2018).
behavioral disorders (3 papers, 2016 to 2021). "Genes linked to congenital and behavioral disorders included dynein axonemal intermediate chain 1, Rho GTPase Activating Protein 36, ATPase Na+/K+ Transporting Subunit Alpha 3 and 5-Hydroxytryptamine Receptor 2C while genes related to fitness effects include genes such as Cysteine-Three-Histidine." (PMID 34209092, 2021). "Three out of seven genes (i.e., HTR2C, MAOA, and OFD1) were previously associated with behavioral disorders in humans, such as aggressive behavior, antisocial personality, and low frustration tolerance." (PMID 33800722, 2021).
migraines (3 papers, 2022 to 2025). "Briefly, 5-HT and its receptors, such as HTR2A, HTR2C are implicated in migraines." (PMID 36079577, 2022).
Parkinsonism (3 papers, 2012 to 2022). Characteristic neurologic anomaly resulting from degeneration of dopamine-generating cells in the substantia nigra, a region of the midbrain, characterized clinically by shaking, rigidity, slowness of movement and difficulty with walking and gait. "Therefore, future studies should analyze the possible interaction between CYP2D6 gene variants and the variants of the SLC6A3, HTR2C and HTR6 genes on the risk for haloperidol-induced parkinsonism." (PMID 36551993, 2022).
asthma (2 papers, 2018 to 2023). "HTR2C, CYP1B1, CYP19A1, ESR1, ESR2, PDR, and AR are found to be interrelated to hormonal disorders; ABCC1, NQO1, TIMP1, ADRB2, and ALOX5 are associated with asthma." (PMID 29861771, 2018).
breast carcinoma (2 papers, 2021 to 2023). "The expression levels of HTR1A, HTR1B, HTR2A, HTR2B, HTR2C, HTR4, and HTR7 were significantly downregulated in highly malignant breast cancer types." (PMID 37795441, 2023). "However, when compared to normal breast tissue, HTR1A, HTR1B, HTR2A, HTR2B, HTR2C, HTR4, and HTR7 were suppressed in high malignancy breast cancer types, whereas they were highly expressed in low malignant breast cancer." (PMID 37795441, 2023).
breast tumor (2 papers, 2009 to 2018). "Kishore and Stamm reported that SNORD115 was essential for correct splicing of a serotonin receptor Htr2c, whose expression has been correlated with breast tumor progression." (PMID 30647841, 2018).
glioblastoma (2 papers, 2013 to 2024). The most malignant astrocytic tumor (WHO grade IV). "The high expression of HTR1D and HTR2C was negatively related to the OS of HNSC, and almost all the HTGPCR genes, except HTR1B and HTR4, were related to the prognosis of glioblastoma." (PMID 39766808, 2024).
memory impairment (2 papers, 2012 to 2024). "Genes involved in neuroactive ligand–receptor interactions, such as Npy2r, Htr2c, and Rxfp1, were significantly dysregulated during cognitive dysfunction or memory impairment which was tightly related with tinnitus." (PMID 38562529, 2024). "Moreover, converging evidence showed that the administration of Htr2c/Htr2a agonists led to short-term memory and long-term memory impairment." (PMID 22359574, 2012).
Stroke (2 papers, 2022 to 2025). Sudden impairment of blood flow to a part of the brain due to occlusion or rupture of an artery to the brain. "This elicits the potential that Htr2c may be a thinkable clinical target for those I/R-mediated stroke patients in the future." (PMID 35502892, 2022). "Eight common genes were found across all three compounds and stroke: MAPK1, PRKCB, PRKCG, HDAC1, HTR1A, HTR2A, HTR2C, and HTR7." (PMID 41011194, 2025).
alcohol use disorder (1 paper, 2025). "Although Htr2c’s role in addiction and reward mechanisms is unclear, a recent pilot study suggested that its agonist reduced self-reported alcohol and amphetamine-type substance use and cravings in participants with alcohol use disorder and MA use disorder, respectively." (PMID 41188933, 2025).
amyotrophic lateral sclerosis (1 paper, 2014). Amyotrophic lateral sclerosis (ALS) is a neurodegenerative disease characterized by progressive muscular paralysis reflecting degeneration of motor neurons in the primary motor cortex, corticospinal tracts, brainstem and spinal cord. "This cascade of events may suggest a mechanism in which two central genes affected by novel nonsense SNPs identified in this study, XIAP and HTR2C, are involved in various neurological diseases such as amyotrophic lateral sclerosis." (PMID 24416366, 2014).
autism spectrum disorder (1 paper, 2021). A spectrum of developmental disorders that includes autism, and Asperger syndrome. "5-Hydroxytryptamine receptor 2C has been associated with neuropsychiatric disorders including autism spectrum disorder, leaving it unclear whether the heterozygous ABCA13 deletion caused the autism spectrum disorder-like phenotypes." (PMID 33478937, 2021).